ALOX5 (arachidonate 5-lipoxygenase)
Diseases named in the same sentence as ALOX5 in open-access papers (continued):
Sharing a sentence is not in itself a finding about the gene and the disease.
lymphoma (3 papers, 2022 to 2023). A malignant (clonal) proliferation of B- lymphocytes or T- lymphocytes which involves the lymph nodes, bone marrow and/or extranodal sites. "Therefore, it may be a promising therapeutic strategy to treat 17p-deleted lymphomas with both ALOX5 and COX-2 inhibitors." (PMID 36750552, 2023). "Conversely, the only ALOX family gene outside of chromosome 17p, ALOX5 on chromosome 10, did not have the same tumor-suppressing role in our mouse lymphoma model." (PMID 36750552, 2023). "ALOX15B and ALOX12 in lymphoma have been reported to have a tumor-suppressive role in promoting murine lymphomas, while ALOX5, the only one not on chromosome 17p, seems to be required at least for some types of leukemia." (PMID 36750552, 2023).
pancreatic ductal adenocarcinoma (3 papers, 2015 to 2024). An infiltrating adenocarcinoma that arises from the epithelial cells of the pancreas. "Inhibition of ALOX5 operated by the microsomal glutathione S-transferase 1 (MGST1) was observed to be consistent in human pancreatic ductal adenocarcinoma (PDAC) cell lines, remarking on ALOX5 role as a positive regulator of ferroptosis." (PMID 37132605, 2024).
parasitemia (3 papers, 2013 to 2021). "In contrast, parasitemia levels were similar in infected WT and Alox5−/− mice." (PMID 23613965, 2013).
preeclampsia (3 papers, 2017 to 2024). Preeclampsia is a hypertensive disorder of pregnancy that is characterized by new-onset hypertension with proteinuria presenting after 20 weeks of gestation, and depending on mild or severe forms may initially present with severe headache, visual disturbances, and hyperreflexia. "An increased expression of ACSL-4 and ALOX-5 together with decreased GPX4 levels in the placenta has been associated with trophoblastic ferroptosis and different obstetric complications such as preeclampsia." (PMID 38790696, 2024). "Previous works have showed that the placental tissue of women with preeclampsia display an enhanced expression of ALOX-5, as well as the fact that they are involved in lipoxin A4 (LXA4) deficiency." (PMID 36671505, 2023).
psoriasis (3 papers, 2015 to 2020). An autoimmune condition characterized by red, well-delineated plaques with silvery scales that are usually on the extensor surfaces and scalp. "To ensure the human relevance, we examined the mRNA expressions of LTA4H, ALOX5, and LTB4R (a human LTB4 receptor) in human psoriasis lesions, using a public microarray data set23." (PMID 30089836, 2018).
psychosis (3 papers, 2023 to 2025). "In the placenta of women with a first episode of psychosis during pregnancy, ALOX5 expression is significantly elevated along with increased iron deposition." (PMID 38503553, 2024). "Our results demonstrate an increased presence of iron deposits that are accompanied by a further expression of TFRC, ACSL-4, ALOX-5, MDA, and GPX4—all of which are observed in the placenta tissue of women who have suffered from a first episode of psychosis." (PMID 36671505, 2023).
pulmonary fibrosis (3 papers, 2011 to 2021). Chronic progressive interstitial lung disorder characterized by the replacement of the lung tissue by connective tissue, leading to progressive dyspnea, respiratory failure, or right heart failure. "Prostaglandin G/H synthase 1 (PTGS1), arachidonate 5-lipoxygenase, and several other targets are associated with arachidonic acid metabolism, which is probably associated with progression of inflammation related to pulmonary fibrosis." (PMID 30092799, 2018).
systemic sclerosis (3 papers, 2022 to 2025). A chronic disorder, possibly autoimmune, marked by excessive production of collagen which results in hardening and thickening of body tissues. "Studies have identified a significant upregulation of ALOX-5 expression and elevated concentrations of LTB4 in the dermal layers of patients with systemic sclerosis." (PMID 41002951, 2025).
tuberculosis (3 papers, 2014 to 2023). A chronic, recurrent infection caused by the bacterium Mycobacterium tuberculosis. "For example, it was previously reported that VNTRs in the IL1RA and ALOX5 genes might be associated with susceptibility to tuberculosis in humans." (PMID 24625963, 2014). "For the genetic epidemiology of tuberculosis, there are only two reports on the association between VNTRs (in the 5-lipoxygenase (ALOX5) and interleukin 1 receptor agonist (IL1RA) genes) and tuberculosis susceptibility in case-control studies." (PMID 24625963, 2014).
aneurysm (2 papers, 2018 to 2025). Bulging or ballooning in an area of an artery secondary to arterial wall weakening. "Importantly, ALOX5 expression in aneurysm wall tissues is obviously increased." (PMID 40289758, 2025).
Anxiety (2 papers, 2011 to 2025). Intense feelings of nervousness, tension, or panic often arise in response to interpersonal stresses. "ALOX5 has also been reported to alter neuronal function, which may explain why mice lacking ALOX5 display increased defensive behaviors against anxiety (Joshi and Praticò, 2011)." (PMID 40370665, 2025).
apical periodontitis (2 papers, 2022 to 2023). "During apical periodontitis development, synthesis of genes that encode 5-LO (Alox5) and 5-lipoxygenase activating protein (FLAP; Alox5ap) were upregulated at 14 days (p <0.05) and down regulated latter on (p <0.05)." (PMID 36287497, 2022).
autoimmune uveitis (2 papers, 2020 to 2024). An autoimmune form of uveitis (disease). "LXA4-deficient Alox5-/- mice and adoptive transfer in T cell-deficient mice also demonstrated that in vivo disruption of the LXA4 pathway amplifies effector T cell responses in autoimmune uveitis." (PMID 32118582, 2020). "T cells from LXA4-deficient (Alox5-/-) mice exhibited enhanced effector function with augmented cytokine production and altered metabolism that resulted in exacerbated disease, while LXA4 treatment in wild type (WT) mice attenuated development of autoimmune uveitis." (PMID 32118582, 2020).
chronic kidney disease (2 papers, 2024). Impairment of the renal function secondary to chronic kidney damage persisting for three or more months. "For example, Alox5 mediates acute injury and has been implicated in interstitial fibrosis and chronic kidney disease (CKD) progression." (PMID 39064752, 2024). "Monocytes from end-stage renal disease (ESRD) patients have increased ALOX5 expression and after 6 days training, they exhibit enhanced TNF-α and IL-6 production to lipopolysaccharide (LPS)." (PMID 38980302, 2024).
diffuse large B-cell lymphoma (2 papers, 2025). "The ALOX5 gene, encoding arachidonate 5-lipoxygenase, is highly expressed in approximately 50% patients with germinal center B cell (GCB)-like diffuse large B-cell lymphoma (DLBCL), correlating with susceptibility to ferroptosis." (PMID 41462004, 2025).
endometrial cancer (2 papers, 2020). Primary or metastatic malignant neoplasm involving the endometrium (mucous membrane that lines the endometrial cavity). "(2019), there is a significant increase in ALOX5 (5-LOX) mRNA expression in type II endometrial cancer compared to normal endometrium and elevated ALOX5 expression is associated with adverse outcomes." (PMID 32982722, 2020).
epilepsy (2 papers, 2024 to 2025). A brain disorder characterized by episodes of abnormally increased neuronal discharge resulting in transient episodes of sensory or motor neurological dysfunction, or psychic dysfunction. "Behavioral tests showed that the neuron-specific deletion of Alox5 improves diverse neuropsychiatric comorbidities observed in this model of epilepsy, especially anxiety, cognitive deficit and autistic-like behavior (assessed by social interaction test)." (PMID 39937026, 2025).
hepatic disease (2 papers, 2018 to 2019). "Arachidonate 5-lipoxygenase (ALOX5) plays a role in the synthesis of leukotrienes from arachidonic acid, and inhibition of the ALOX5 pathway markedly reduces the number of Kupffer cells in culture and attenuates inflammation and fibrosis in experimental liver disease." (PMID 30923657, 2019).
Huntington disease (2 papers, 2025). Huntington disease (HD) is a rare neurodegenerative disorder of the central nervous system characterized by unwanted choreatic movements, behavioral and psychiatric disturbances and dementia. "In Huntington’s disease models, ALOX5 has been identified as a key factor in HTT-Q94-induced, ACSL4-independent ferroptosis, emphasizing its independent role in ferroptosis, particularly in neurodegenerative diseases." (PMID 40191227, 2025). "In summary, these results demonstrated that Alox5 was crucial for mutant huntingtin (Mhtt)‐mediated ferroptosis and suggested that Alox5 was a new target for treating Huntington's disease." (PMID 40485049, 2025). "Moreover, ALOX5 is a critical factor in Huntington’s disease, and its inhibition has been shown to significantly improve behavioral deficits and reduce neuronal damage." (PMID 40191227, 2025). "Notably, inactivation of the Alox5 gene eliminated iron removal in the striatal neurons of Huntington's disease (HD) mice." (PMID 40485049, 2025).
Hyperglycemia (2 papers, 2019 to 2020). An increased concentration of glucose in the blood. "Interestingly, unlike ALOX5 and LTBR4, MYD88 expression was not modulated by hyperglycemia." (PMID 32273829, 2020).
intracerebral haemorrhage (2 papers, 2021 to 2022). "Intracerebral hemorrhage injury can be alleviated by the administration of ferroptosis inhibitors, the mechanism of which is mainly related to iron overload, decreased expression of glutathione peroxidase 4, and increased activity of arachidonic acid-dependent lipoxygenase-5 (ALOX5)." (PMID 34413966, 2021).
ovarian tumor (2 papers, 2018 to 2023). "The unbiased approach showed that expression of ALOX5 and ALOX12B are significantly higher in “high” expressing group, compared to the “low” expressing group, in the TCGA ovarian tumor cohort (n = 216; ALOX5 p = 0.00108 and ALOX12B p = 0.00248) as well as in other tumor cohorts." (PMID 30258081, 2018).
Parkinson disease (2 papers, 2024). A progressive degenerative disorder of the central nervous system characterized by loss of dopamine producing neurons in the substantia nigra and the presence of Lewy bodies in the substantia nigra and locus coeruleus. "Recent findings have shown that the inhibition of ALOX5 attenuated the accumulation of lipid peroxides and neuronal damage and prevented ferroptosis in a model of Parkinson’s disease." (PMID 38474262, 2024). "On the other hand, specific inhibition of the pro-inflammatory ALOX5 slowed down the rate of neurodegeneration in a Parkinson disease model suggesting a patho-physiological role for this enzyme." (PMID 39511487, 2024).
primary progressive MS (2 papers, 2008 to 2024). "Interestingly, we previously found an up-regulation of ALOX5 in both secondary progressive and primary progressive MS patients." (PMID 18366677, 2008).
rectal cancer (2 papers, 2021 to 2023). A primary or metastatic malignant neoplasm that affects the rectum. "To further determine the reason why decreased expression of ALOX5 can improve the prognosis of rectal cancer patients, we continued to transfect ALOX5 siRNAs into HCT8 and HCT116 cells to investigate whether ALOX5 plays a role in CRC tumorigenesis." (PMID 37144561, 2023).
abdominal aortic aneurysm (1 paper, 2025). Enlargement and ballooning of the vessel that supplies arterial blood to the abdomen, pelvis and legs. "This suggested that ALOX5 inhibition improved the histopathological damage of the wall of abdominal aortic aneurysm in mice." (PMID 40781109, 2025).
aneurysmal disease (1 paper, 2013). "Changes in the macrophage polarization are paralleled by clear, but selective changes for markers such as cathepsin K and S, and ALOX5 which have been linked to macrophage differentiation as well as aneurysmal disease." (PMID 23349755, 2013).
aortic valve disease (1 paper, 2024). "Additionally, AS from LVH demonstrates upregulated anti-inflammatory COX receptor-related genes PTGER2 and PTGER4, and LOX-derived LT receptor-related gene CYSLTR2, but downregulated TBXAS1 and ALOX5, suggesting different mechanisms causing aortic valve disease and aortic calcification." (PMID 39062733, 2024).
breast adenocarcinoma (1 paper, 2018). "In contrast, ALOX5 expression was increased significantly in gefitinib‐resistant cells, as well as paclitaxel‐resistant breast adenocarcinoma cells (MDA‐MB‐231)." (PMID 29901268, 2018).
bronchitis (1 paper, 2017). An acute or chronic inflammatory process affecting the bronchi. "Significant differences in the prevalence and risk of bronchitis were found in genotypes of LT-α and TNF-α, but not in ALOX5, LTC4S, TBXA2R, ADAM33, NOS1 and ORMDL3 in the Inuit populations residing both in Greenland and in Denmark." (PMID 28740106, 2017).
carcinoma in situ (1 paper, 2025). "Moreover, mice with intact JMJD3 in the gastric epithelium not only developed carcinoma in situ under MNU induction, but also showed significantly higher expression of ALOX5 in the gastric epithelium compared to the KO group." (PMID 41184226, 2025).
chronic asthma (1 paper, 2022). An asthma that is characterized by the development of persistent airway inflammation and recurrent attacks of breathlessness and wheezing, which vary in severity and frequency. "For example, zileuton, a selective ALOX5 inhibitor, is used to prevent and treat chronic asthma." (PMID 35444656, 2022).
chronic obstructive pulmonary disease (1 paper, 2020). A chronic and progressive lung disorder characterized by the loss of elasticity of the bronchial tree and the air sacs, destruction of the air sacs wall, thickening of the bronchial wall, and mucous accumulation in the bronchial tree. "ALOX5 expression is known to be involved in carcinogenesis and is also involved in chronic obstructive pulmonary disease (COPD)." (PMID 32961854, 2020).
cleidocranial dysostosis (1 paper, 2020). "In this context, repairing RUNX2 gene mutation in iPSCs derived from cleidocranial dysostosis patients as well as transducing nuclear matrix protein SATB2 and Alox5 gene into iPSCs promoted osteodifferentiation." (PMID 32300365, 2020).
cognitive decline (1 paper, 2021). "However, studies on the modulation of ALOX5 gene expression are still at an early stage, and the role of ALOX5 in cognitive decline remains unclear." (PMID 34199148, 2021).
colon adenocarcinoma (1 paper, 2023). "To achieve this, we filtered the 785 colon adenocarcinoma patient data set using the differentially expressed genes involved in the bile acid pathway biosynthesis along with the ALOX5 and PTGS2 genes." (PMID 37458451, 2023).
colorectal tumor (1 paper, 2022). "They showed that the expression level of ALOXE3, ALOX5, ALOX12, and ALOX12B was upregulated in colorectal tumor samples." (PMID 35928873, 2022).
conjunctivitis (1 paper, 2025). Inflammation of the conjunctiva of the eye. "Furthermore, all wild-type mice but only 41% and 28% of Alox5–/– and Ltb4r1–/– mice, respectively, developed conjunctivitis, which, in those Alox5–/– and Ltb4r1–/– mice developing it, was also milder than in wild-type mice." (PMID 40985889, 2025).
cystic fibrosis (1 paper, 2024). Autosomal recessive disorder caused by pathogenic variants in the CFTR gene (cystic fibrosis transmembrane conductance regulator), which encodes a chloride and bicarbonate channel expressed in epithelial cells, and follow the diagnosis criteria. "Because of this, ALOX5 and the leukotrienes have been consistently involved in the pathogenesis in several acute and chronic inflammatory human diseases like cystic fibrosis, asthma and cancer." (PMID 38612771, 2024).
developmental delay (1 paper, 2022). "Combining the Gene ontology analysis results and Human Brain Transcriptome database, we showed that FGFR3 and ALOX5 could serve as novel developmental delay candidate genes." (PMID 36358993, 2022). "These outcomes indicated the potential relationship between FGFR3, ALOX5, and developmental delay." (PMID 36358993, 2022).
experimental autoimmune encephalomyelitis (1 paper, 2021). An autoimmune demyelinating disease of the central nervous system that is produced experimentally in animals by the injection of homogenized brain or spinal cord in Freund's adjuvant. "In experimental autoimmune encephalomyelitis (EAE), Alox5-KI mice displayed an earlier disease onset and a significantly higher cumulative incidence rate than wildtype controls but the clinical score kinetics were not significantly different." (PMID 34677413, 2021).
fragile X syndrome (1 paper, 2022). A genetic syndrome caused by mutations in the FMR1 gene which is responsible for the expression of the fragile X mental retardation 1 protein. "This set of genes included cancer oncogenes (CMYC, CKIT, BCL2, KRAS) and genes associated with different cancer types (ADAM12, ALOX5, SRSF6, VEGF12) as well as FMR1, associated with fragile X syndrome (OMIM: 300624), and SNX12, which is associated with neurodegenerative diseases." (PMID 35573091, 2022).
haemorrhage (1 paper, 2021). "ALOX5, arachidonate 5-lipoxygenase; eNOS, endothelial nitric oxide synthase; FLAP, 5-lipoxygenase-activating protein; PGIS, prostacyclin synthase; UGIH, upper gastrointestinal haemorrhage." (PMID 34620931, 2021).
ichthyosis (1 paper, 2020). Disorders of cornification that are characterized by visible scaling and/or hyperkeratosis of most or all of the skin. "Additionally, 15 genes involved in lipid metabolism were differentially expressed, some directly involved in ichthyosis, e.g., ABCA12, ALOX5, ALOX12B, ALOXE3, CYP4F2, and 2 elongation of very long chain fatty acid protein (ELOV) genes." (PMID 32544098, 2020).
kidney cancer (1 paper, 2024). Primary or metastatic malignant neoplasm involving the kidney. "In a previous study, we analyzed the methylation status of our three markers and found ALOX5 to be highly methylated in 2/3 prostate and 1/3 kidney cancer cell lines." (PMID 39587670, 2024).
lupus nephritis (1 paper, 2025). Glomerulonephritis in the context of systemic lupus erythematosus. "This pharmacological profiling suggests both ALOX5 and PTGER2 represent promising therapeutic targets for further investigation in lupus nephritis." (PMID 40290492, 2025).
lymphoid leukemia (1 paper, 2017). A malignant lymphocytic neoplasm of B-cell or T-cell lineage involving primarily the bone marrow and the peripheral blood. "Nonetheless, there was no significant influence of Alox5 deficiency on normal hematopoietic stem cells (HSCs) or on the induction of lymphoid leukemia by BCR-ABL26." (PMID 28500307, 2017).